ZNF384 (zinc finger protein 384)
Description:
Transcription factor that binds the consensus DNA sequence [GC]AAAAA. Seems to bind and regulate the promoters of MMP1, MMP3, MMP7 and COL1A1 (By similarity).
Synonyms: CAGH1; CIZ; NMP4; TNRC1; CAGH1A; NP; ERDA2
Tractability: PROTAC: ubiquitination databases record sites on it; its protein half-life has been measured.
Gene: Protein-coding gene on chromosome 12 (6,666,477 to 6,689,572, reverse strand). Ensembl gene ENSG00000126746.
Subcellular location: Nucleus
Subcellular location (Human Protein Atlas): Nucleoplasm
Gene Ontology:
Molecular function: sequence-specific double-stranded DNA binding; transcription cis-regulatory region binding
Biological process: regulation of transcription by RNA polymerase II
Cellular component: nucleus
Genetic constraint (gnomAD): Loss-of-function variants: 12 observed, 62.39 expected, observed/expected ratio (o/e) 0.19, 90% interval 0.12 to 0.31. The upper end of that interval is the gene's LOEUF score, 0.31, which puts it in group 1 of 6, group 1 being the genes least tolerant of losing a copy. Missense variants: 458 observed, 678.12 expected, observed/expected ratio (o/e) 0.68, 90% interval 0.62 to 0.73. Synonymous variants: 258 observed, 265.27 expected, observed/expected ratio (o/e) 0.97, 90% interval 0.88 to 1.08.
Homologues: Orthologues: macaque ZNF384 (98% identical), dog ZNF384 (98% identical), pig ZNF384 (97% identical), rabbit ZNF384 (94% identical), chimpanzee ZNF384 (92% identical), guinea pig ZNF384 (92% identical), mouse Zfp384 (92% identical), rat Zfp384 (86% identical), tropical clawed frog znf384 (63% identical), zebrafish znf384a (54% identical), zebrafish znf384b (35% identical). Paralogues in human: ZNF362 (33% identical), ZNF143 (16% identical), PATZ1 (15% identical), MTF1 (14% identical), ZNF76 (14% identical), PRDM1 (14% identical), PRDM10 (14% identical), ZBTB16 (13% identical), ZNF451 (13% identical), HIC1 (13% identical), PRDM14 (13% identical), ZNF281 (13% identical), and 24 more.
Diseases named in the same sentence as ZNF384 in open-access papers:
ZNF384 is named in the same sentence as 50 diseases in open-access papers, as found by Europe PMC text mining. Sharing a sentence is not in itself a finding about the gene and the disease. The quoted sentences say what the papers report.
acute lymphoblastic leukemia (21 papers, 2013 to 2025). Leukemia with an acute onset, characterized by the presence of lymphoblasts in the bone marrow and the peripheral blood. "Anomalous expression of ZNF384 is associated with acute lymphoblastic leukemia (ALL), high-grade gliomas, hepatocellular carcinoma, and so on." (PMID 35669784, 2022). "Acute leukemia with TCF3::ZNF384 is a distinct type of acute leukemia that present most commonly as B-acute lymphoblastic leukemia or mixed-phenotype acute leukemia (B/myeloid)." (PMID 39531055, 2025). "The rearrangement of the RNA-binding protein EWSR1 characterizes a variety of malignant tumors, including Ewing’s sarcoma (EWSR1/ETS), depilated small round cell tumor (EWSR1/WT1), and some acute lymphoblastic leukemia (EWSR1/ZNF384)." (PMID 35686089, 2022). "Recently, fusion genes involving ZNF384 have been identified in B-cell precursor acute lymphoblastic leukemia; eight fusion partners have been reported for the ZNF384 gene." (PMID 34211850, 2021). "ZNF384 is a part of a fusion gene pair found in B-cell precursor acute lymphoblastic leukemia (ALL)." (PMID 32857815, 2020). "Rearrangements of the RNA binding protein, EWSR1, characterize various malignancies including Ewing sarcoma (EWSR1/ETS), desmoplastic small round cell tumor (EWSR1/WT1), and some acute lymphoblastic leukemias (EWSR1/ZNF384)." (PMID 23637631, 2013). "ZNF384 is a zinc finger protein mainly investigated in acute lymphoblastic leukemia (ALL)." (PMID 35669784, 2022). "ZNF384‐fusion (Z‐fusion) genes were recently identified in B‐cell acute lymphoblastic leukemia (B‐ALL) and are frequent in Japanese adult patients." (PMID 39015025, 2024). "ZNF384‐fusion genes were recently identified in B‐cell acute lymphoblastic leukemia (B‐ALL) and are frequent in Japanese adult patients." (PMID 39015025, 2024). "Previous studies have shown that, the clinical features and prognosis of ZNF384-rearranged pediatric acute lymphoblastic leukemia (ALL) depend on its translocation partners." (PMID 36052266, 2022). "Novel recurrent fusion gene types such as zinc finger protein 384 (ZNF384) fusions have been identified in B-cell precursor acute lymphoblastic leukemia (BCP-ALL) with the application of next-generation sequencing technologies." (PMID 33816270, 2021). "It is typically necessary to prove the diagnosis of secondary tumors, rather than a lineage switch at relapse, for types of leukemia that demonstrate increased lineage plasticity, such as AL with KMT2A, ZNF384 or DUX4 gene rearrangements or early T-cell acute lymphoblastic leukemia (ETP-ALL)." (PMID 40565358, 2025). "Novel fusion genes such as ZNF384, have been identified in B-cell precursor acute lymphoblastic leukemia (BCP-ALL) in recent years." (PMID 35164825, 2022). "Critically, recurrent chromosomal translocations involving the ZNF384 gene, which result in fusion proteins with partners such as EWSR1, TAF15, and EP300, are frequently observed in the pathogenesis of acute lymphoblastic leukemia (ALL)." (PMID 41429980, 2025).
leukemia (19 papers, 2012 to 2025). A malignant (clonal) hematologic disorder, involving hematopoietic stem cells and characterized by the presence of primitive or atypical myeloid or lymphoid cells in the bone marrow and the blood. "This is the first presentation of leukemia with TCF3::ZNF384 fusion as an isolated mediastinal tumor." (PMID 39531055, 2025). "We present a unique case of an adult with mixed lineage leukemia with TCF3::ZNF384 fusion presenting as an indolent isolated mediastinal mass." (PMID 39531055, 2025). "We report the first case of TCF3::ZNF384 mixed-phenotype leukemia presenting as isolated extramedullary disease in the mediastinum." (PMID 39531055, 2025). "While both these proteins have been studied in the context of carcinogenesis, reports related to leukemia are more common for ZNF384." (PMID 37175757, 2023). "These inhibitors can also be utilized to treat ZNF384 leukemia; nevertheless, prospective randomized trials are scarce." (PMID 35875063, 2022). "Similar to our preliminary transcriptome sequencing results (unpublished data), a report from Japanese Adult Leukemia Study Group (JALSG) showed that ZNF384 fusions had the highest frequency among all novel fusions in adult Ph-negative BCP-ALL." (PMID 33816270, 2021). "CBFB and ZNF384 are cancer genes for leukemia; RB1 is a gene for retinoblastoma, sarcoma and small-cell lung cancers and MAP3K4 is a gene for pancreatic, breast and colorectal cancers, as listed on the Cancer Gene Census." (PMID 33087126, 2020). "A notable exception is the overexpression of SALL4 in the ZNF384-rearranged group, which has been described as an oncogene in leukemia." (PMID 28806978, 2017). "In addition, the development of other methods to detect ZNF384 specific translocation partners and leukemia specific targeting agents is of great significance to further improve the prognosis of ALL with ZNF384-rearrangement." (PMID 36052266, 2022). "Gilteritinib treatment led to a marked delay in leukemia progression compared to vehicle control (panel e: P < 0.005, panel g: P < 0.005) and also longer leukemia-free survival (panel f: P = 0.0027, panel h: P = 0.0026), despite variation in the in vivo growth rate of these two ZNF384-r ALL models." (PMID 36104354, 2022). "Indeed, studies analysing drug responsiveness in ZNF384- and MLL/KMT2A-childhood ALL, suggested that FLT3 targeting therapy could be considered in these forms of leukaemia, especially in ZNF384-ALL." (PMID 38049555, 2024). "In patient-derived xenograft models of ZNF384-rearranged ALL, gilteritinib exhibits significant anti-leukemia efficacy as a monotherapy in vivo." (PMID 36104354, 2022). "But at least in ZNF384-r ALL, there seems to be a dependency of FLT3 signaling although its exact contribution to leukemogenesis and leukemia maintenance remains unclear." (PMID 36104354, 2022).
acute leukemia (9 papers, 2014 to 2025). A clonal (malignant) hematopoietic disorder with an acute onset, affecting the bone marrow and the peripheral blood. "ZNF384 fusions to TAF15 and Ewing’s sarcoma gene EWSR1, caused by chromosome translocations have been implicated in acute leukemia." (PMID 24465633, 2014). "Functional studies proved that ZNF384 fusion could block the differentiation of early B lymphocytes and induce acute leukemia in mouse models." (PMID 32980888, 2020).
breast carcinoma (7 papers, 2019 to 2025). "Infrequent mutations in CBFB, MAP3K4 and ZNF384 are enriched in Stage I, together with classic breast cancer gene AKT1." (PMID 33087126, 2020). "Therefore, our research focused on ZNF384 regulation of the malignant phenotype of breast cancer and the underlying molecular mechanisms." (PMID 36100877, 2022). "Furthermore, research studies have shown that ZNF384 gene mutation in breast cancer tissues and cells may change its gene expression level to delay the course of disease and extend patient survival." (PMID 40717692, 2025). "It is reported that overexpression of ZNF384 has oncogenic potential for some solid tumors, such as hepatocellular carcinoma and breast cancer." (PMID 39015025, 2024). "We discovered that ZNF384 is overexpressed in breast cancer and is predictive of a poor prognosis in patients with breast cancer." (PMID 36100877, 2022). "To investigate the role of ZNF384 in breast cancer progression, we determined the expression levels of ZNF384 in 20 cases of primary breast cancer tissues and the paired adjacent normal tissues by Immunohistochemistry (IHC)." (PMID 36100877, 2022). "ZNF384 is mainly localized in the nucleus and is overexpressed in breast cancer tissues than normal breast tissue." (PMID 36100877, 2022). "Epithelial-mesenchymal transformation (EMT) is involved in the metastasis process in all types of human cancer; therefore, we evaluated the effect of ZNF384 on EMT in breast cancer." (PMID 36100877, 2022). "Together, these findings indicate that ZNF384 contributes to breast cancer progression by transactivating ZEB1 expression." (PMID 36100877, 2022). "To further investigate the role of ZNF384 in breast cancer progression, we transfected a human ZNF384 expression vector into T47D and ZR-75-30 cells." (PMID 36100877, 2022). "We noted that ZNF384 was significantly overexpressed in breast cancer and highlighted the oncogenic mechanism of ZNF384." (PMID 36100877, 2022). "Herein, the probed tumorigenic role of ZNF384 in breast cancer expands the current EMT network, including ZEB1." (PMID 36100877, 2022). "The findings suggest that ZNF384 can serve as a prognostic factor and a therapeutic target for breast cancer patients." (PMID 36100877, 2022). "To assess the role of ZNF384 in breast cancer progression in vivo, we implanted shZNF384 and shControl cells into mice mammary fat pads and tail vein, respectively." (PMID 36100877, 2022). "In breast cancer cells, ZNF384 directly transactivated ZEB1 expression by binding to the activation of the promotor." (PMID 36100877, 2022). "Recent research revealed that ZNF384 can stimulate MCF-7 breast cancer growth by regulating cell cycle and metastasis-related genes via an ER alpha dependent pathway." (PMID 30957858, 2019). "Overall, our study demonstrates a novel mechanism of breast metastasis, suggesting that targeting ZNF384 may be an effective strategy for breast cancer therapy." (PMID 36100877, 2022). "Together, these findings suggest that ZNF384 induces an EMT-like phenotype in breast cancer." (PMID 36100877, 2022). "Here, we investigated the role of ZNF384 in breast cancer metastasis." (PMID 36100877, 2022). "Moreover, ZNF384 expression was up-egulated in six different breast cancer cell lines compared with the normal breast cell line MCF10A by western blot." (PMID 36100877, 2022). "Similar to the results of gain-of-function assays, the depletion of ZNF384 did not affect the cell proliferation in vitro, whereas ZNF384 depletion could promote breast cancer migration and invasion in vitro." (PMID 36100877, 2022). "Together, these findings indicate that ZNF384 contributes to breast cancer metastasis." (PMID 36100877, 2022). "Together, these findings indicate that ZNF384 acts as an oncogene in breast cancer." (PMID 36100877, 2022). "Although ZNF384 is overexpressed in several types of human cancer, the role of ZNF384 in breast cancer remains unknown." (PMID 36100877, 2022).
breast carcinoma (continued). "We propose that ZNF384 can serve as a prognostic factor and target patients with breast cancer." (PMID 36100877, 2022). "Together, these findings indicate that ZNF384 may contribute to breast cancer progression." (PMID 36100877, 2022). "Specifically, ZNF384 was upregulated and transcriptionally activated ZEB1 to facilitate EMT in breast cancer." (PMID 40717692, 2025). "ZNF384 directly transactivates ZEB1 expression and induces an EMT-like phenotype and breast cancer metastasis." (PMID 36100877, 2022). "Here, we identified that ZNF384 is an important bridging element in the EMT network, playing a tumorigenic role in metastatic progression in breast cancer cells." (PMID 36100877, 2022). "ZNF384 transactivated ZEB1 expression and induced an epithelial and mesenchymal-like phenotype, resulting in breast cancer metastasis." (PMID 36100877, 2022).
hepatocellular carcinoma (6 papers, 2019 to 2025). A malignant tumor that arises from hepatocytes. "Surprisingly, research studies have indicated that METTL3 mediated m6A modification of ZNF384, which in turn stabilized ZNF384 mRNA and facilitated the advancement of hepatocellular carcinoma." (PMID 40717692, 2025). "ZNF384, a recently found transcription factor with the zinc finger domain, exhibits consistently high expression in lung cancer, hepatocellular cancer, colorectal cancer, and osteosarcoma." (PMID 36100877, 2022). "Overexpression of zinc finger protein 384 (ZNF384), a poor prognostic predictor, has been found to promote cell growth by upregulating the expression of Cyclin D1 in hepatocellular carcinoma." (PMID 40599863, 2025).
B-cell precursor acute lymphoblastic leukemia (5 papers, 2018 to 2024). "Zinc-finger protein 384 (ZNF384) fusions are an emerging subtype of precursor B-cell acute lymphoblastic leukaemia (pre-B-ALL) and here we further characterised their prevalence, survival outcomes and transcriptome." (PMID 29531323, 2018). "ZNF384 is a C2H2-type zinc finger protein which functions as a transcription factor, and fusion genes with this gene have been reported in ~3% of children with B-cell precursor acute lymphoblastic leukemia." (PMID 31096545, 2019).
acute myeloid leukemia (3 papers, 2020 to 2026). Acute myeloid leukemia (AML) is a group of neoplasms arising from precursor cells committed to the myeloid cell-line differentiation. "Other fusion genes involved EP300, ZNF384 and dozens of other genes have been reported in acute myeloid leukemia (AML) and B-ALL." (PMID 32980888, 2020).
colorectal cancer (3 papers, 2020 to 2023). A primary or metastatic malignant neoplasm that affects the colon or rectum. "Mounting evidence suggested that ZNF384 transactivated multiple downstream oncogenes, including HBO1 and MMP2, highlighting its tumorigenic function in osteosarcoma and colorectal cancer." (PMID 36100877, 2022).
melanoma (3 papers, 2019 to 2021). A malignant, usually aggressive tumor composed of atypical, neoplastic melanocytes. "Furthermore, it is reported that overexpression of ZNF384 can promote metastasis in melanoma cells." (PMID 31168049, 2019).
psoriasis (3 papers, 2022 to 2025). An autoimmune condition characterized by red, well-delineated plaques with silvery scales that are usually on the extensor surfaces and scalp. "ZNF384 is a potential therapeutic target for psoriasis and AD by regulating PPARG, ZNF415, HLX, and ANHX." (PMID 35669784, 2022). "Among inflammatory dermatoses, psoriasis exhibits the strongest overlap with dementia genetics, with shared susceptibility loci including APOE, IL12B, and HLA-DRB5, and transcriptional regulators such as ZNF384 that converge on IL-17/TNF signaling." (PMID 41465136, 2025). "However, the research about ZNF384 in psoriasis and AD is vacant." (PMID 35669784, 2022). "Finally, we found that ZNF384 might regulate STFs, thus influencing psoriasis and AD." (PMID 35669784, 2022).
sarcoma (3 papers, 2014 to 2021). A usually aggressive malignant neoplasm of the soft tissue or bone. "Furthermore, TCGA database showed ZNF384 transcript is upregulated in human sarcoma tissues." (PMID 33754016, 2021).
cervical cancer (2 papers, 2021 to 2025). A primary or metastatic malignant neoplasm involving the cervix. "This increased binding between ZNF384 and the INTS13 promoter region appears to be a crucial mechanism underlying the observed overexpression of INTS13 in cervical cancer tissues." (PMID 41429980, 2025). "The results unequivocally demonstrated a substantially increased binding affinity of ZNF384 to the predicted INTS13 promoter region in primary cervical cancer cells (pCCa-1, pCCa-2, pCCa-3) when compared to human cervical epithelial cells (priCEpi-1)." (PMID 41429980, 2025). "Furthermore, ChIP assays performed on clinical cervical cancer tissues (T1, T2 and T3) revealed significantly enhanced ZNF384 occupancy at the INTS13 promoter locus in contrast to adjacent paracancerous cervical tissues (N1, N2, and N3)." (PMID 41429980, 2025). "To experimentally validate the predicted regulatory interplay between ZNF384 and INTS13, we precisely modulated ZNF384 expression in cervical cancer cells." (PMID 41429980, 2025). "ZNF384 binds to an AT-rich motif in the APOBEC3B (A3B) promoter, and its presence is required for the HPV E6 oncoprotein to activate A3B expression, contributing to HPV-induced carcinogenesis in cervical cancer." (PMID 41429980, 2025).
liver cancer (2 papers, 2019 to 2025). An epithelial or non-epithelial malignant neoplasm that arises from the liver. "ZNF384 was shown to act as a direct transcriptional regulator of Cyclin D1, binding to its promoter region, in liver cancer." (PMID 40405535, 2025). "To explore the role of ZNF384 in the development of HCC, we first verified the expression level of ZNF384 in liver cancer cell lines in order to select appropriate HCC cell lines." (PMID 31168049, 2019).
lung carcinoma (2 papers, 2022 to 2025). "Analysis of the Starbase database indicated that ZNF384 was elevated in lung cancer, but its exact role in NSCLC is still being elucidated." (PMID 40717692, 2025). "Additionally, ZNF384 presented the higher expression in A549 and H1299 cells among all lung cancer cell lines." (PMID 40717692, 2025).
mixed phenotype acute leukemia (2 papers, 2021). An acute leukemia of ambiguous lineage. "ZNF384-, or less commonly, ZNF362-rearranged acute leukemia is a biologically and clinically distinct leukemic subtype present in ~6% of childhood, 7.3% of adult, and 15% of AYA B-ALL, and in 48% of B/myeloid mixed phenotype acute leukemia (MPAL)." (PMID 34501239, 2021).
osteosarcoma (2 papers, 2022 to 2023). A usually aggressive malignant bone-forming mesenchymal neoplasm, predominantly affecting adolescents and young adults. "ZNF384 is possible transcription factor for the histone acetyltransferase HBO1, the latter promoted osteosarcoma cell growth in vitro and in vivo." (PMID 38049415, 2023).